CGA (glycoprotein hormones, alpha polypeptide)
Diseases named in the same sentence as CGA in open-access papers (continued):
Sharing a sentence is not in itself a finding about the gene and the disease.
esophageal SCC (1 paper, 2007). "Analogous to small cell lung cancer, diagnosis of esophageal SCC is aided by immunohistochemical staining for common neuroendocrine markers, including Syn, CgA and NSE." (PMID 17335582, 2007). "Positive labeling with four neuroendocrine markers including Syn, CD56, NSE and CgA was apparent in these cases, which was similar to previous reports of esophageal SCC and pulmonary SCC." (PMID 17335582, 2007). "Higher percentages of positive labeling of Syn, CD56, CgA, NSE, and TTF-1 in esophageal SCC cases implicated that they are valuably applied in differential diagnosis of the malignancy." (PMID 17335582, 2007). "Higher proportion of positive labeling of Syn, CD56, CgA, NSE, and TTF-1 in esophageal SCC implicate that they are valuably applied in differential diagnosis of the malignancy." (PMID 17335582, 2007).
fibrosarcoma (1 paper, 2016). A malignant mesenchymal fibroblastic neoplasm affecting the soft tissue and bone. "In particular, the results obtained in the fibrosarcoma model show that neutralization of endogenous CgA with specific antibodies enhances tumor growth rate, whereas systemic administration of low amounts of exogenous full-length CgA reduces tumor growth." (PMID 27683038, 2016). "Furthermore, the anti-tumor effects of 30 pmol CgA were significantly inhibited by anti-PN1 antibodies, but not by control antibodies in both fibrosarcoma and adenocarcinoma models." (PMID 27683038, 2016).
gingivitis (1 paper, 2024). A disorder involving inflammation of the gums; may affect surrounding and supporting structures of the teeth. "In the present study, it was observed that in both Pr and N-Pr groups, gingivitis patients had higher levels of CgA and AA in comparison to periodontally healthy patients." (PMID 38368525, 2024). "In the N-Pr gingivitis group, a statistically significant decrease was observed in salivary CgA, AA, β-endorphin, DHEA, and sIgA levels after periodontal therapy (p<0.05), with the exclusion of the NPY level which showed no alteration (p>0.05)." (PMID 38368525, 2024). "While Pr gingivitis patients before treatment and the periodontally healthy group showed a significant difference in CgA, AA and β-endorphin values (p<0.05); there was a significant difference in CgA, AA and DHEA values between N-Pr gingivitis patients and periodontal healthy groups (p<0.05)." (PMID 38368525, 2024). "There were no significant changes in salivary CgA, AA, DHEA, sIgA, and neuropeptide Y levels in pregnant women with gingivitis (p>0.05); however, a decrease in β-endorphin levels was observed after therapy (p<0.05)." (PMID 38368525, 2024). "While periodontal therapy showed an improvement in salivary CgA, AA, β-endorphin, DHEA, and sIgA levels (p<0.05) in non-pregnant women with gingivitis; neuropeptide Y levels were found to be unaffected (p>0.05)." (PMID 38368525, 2024).
glomus tumor (1 paper, 2025). A rare benign or malignant mesenchymal neoplasm arising from cells that resemble the modified smooth muscle cells of the glomus body. "In our study, we observed a unique differentiation pattern within the glomus tumor, characterized by the absence of CgA staining and positive expression of Syn." (PMID 39776317, 2025).
Large vessel vasculitis (1 paper, 2016). A type of vasculitis (inflammation of blood vessel walls) affecting large arteries such as the aorta and branches of the aorta. "Until further study clarifies the potential role of CgA-derived polypeptides in large vessel vasculitis, care should be taken with correct prescription of anti-rheumatic and supportive medications, such as PPIs." (PMID 27531191, 2016).
laryngeal (1 paper, 2024). "Then the patient underwent radical resection of the tumor, and postoperative pathology confirmed the diagnosis of laryngeal NET by immunohistochemical staining for Syn (+), CD56 (+), and CgA (+)." (PMID 39259067, 2024).
lateral sclerosis (1 paper, 2014). Primary lateral sclerosis (PLS) is an idiopathic non-familial motor neuron disease characterized by slowly progressive upper motor neuron dysfunction leading to spasticity, mild weakness in voluntary muscle movement, hyperreflexia, and loss of motor speech production. "Recent studies evidenced lower CgA (−44%) levels inamyotrophic lateral sclerosis patients compared with healthy individuals, whereas data on CgA involvement inpsychiatric diseases are not univocal and studies on schizophrenic patients gavecontradictory results." (PMID 24671122, 2014).
lymphocytic colitis (1 paper, 2018). Microscopic colitis characterized by the accumulation of lymphocytes in the colonic epithelium and lamina propria. "Another study not only confirmed these results, but also demonstrated that the significant increase of CgA+ cells in lymphocytic colitis is present both in the right and left colon." (PMID 29382152, 2018).
malignant pheochromocytomas (1 paper, 2014). "In addition, except for malignant pheochromocytomas, WE-14 levels were positively correlated to CgA levels in each group of patients (data not shown)." (PMID 24523932, 2014).
mastocytosis (1 paper, 2024). A clonal myeloproliferative neoplasm characterized by the proliferation and accumulation of neoplastic mast cells in one or multiple organs or organ systems. "Additionally, there is currently no scientific evidence supporting CgA as a biomarker for MC activation in humans, and reported data show no elevation in CgA levels among mastocytosis patients." (PMID 38243020, 2024).
metastasis (1 paper, 2020). The spread or migration of cancer cells from one part of the body (where they first appeared) to another. "Several studies have suggested that CgA is a reliable diagnostic biomarker for PanNETs with increased CgA values associated with higher tumor grade and stage and liver metastasis and might serve as a prognostic marker for both progression-free and overall survival." (PMID 32850899, 2020).
multiple system atrophy (1 paper, 2021). Multiple system atrophy (MSA) is a neurodegenerative disorder characterized by autonomic failure (cardiovascular and/or urinary), parkinsonism, cerebellar impairment and corticospinal signs with a median survival of 6-9 years. "We also measured CSF CgA in multiple system atrophy (MSA) patients, as MSA is characterized by severe orthostatic hypotension." (PMID 33499181, 2021).
Neuroendocrine prostate carcinoma (1 paper, 2023). "Neuroendocrine prostate carcinoma (NEPC) is recognized by neuroendocrine markers such as chromogranin A (CgA), synaptophysin (Syn), and neuron-specific enolase (NSE)." (PMID 38077153, 2023).
orthostatic hypotension (1 paper, 2021). Sudden fall of the blood pressure of at least 20/10 mm Hg when a person stands up. "CSF CgA levels were lower in PD patients with orthostatic hypotension (OH) compared to patients without OH." (PMID 33499181, 2021).
parathyroid carcinoma (1 paper, 2018). "Higher expression of chromogranin A (CgA) further confirmed parathyroid carcinoma as a rare endocrine tumor." (PMID 30290620, 2018). "CgA, Ki-67, and Syn were positive in all the primary and metastatic lesions, suggesting that they might be valuable markers for validating the diagnosis of parathyroid carcinoma." (PMID 30290620, 2018). "Serum PTH and CgA serve as circulating biomarkers in parathyroid carcinoma, and raised levels of PTH and CgA together with locoregional lymphadenopathy may indicate parathyroid carcinoma." (PMID 30290620, 2018).
polycystic ovary syndrome (1 paper, 2025). A disorder that manifests as multiple cysts on the ovaries. "This study investigates serum chromogranin A (CgA) levels and their association with endocrine and metabolic features in patients with polycystic ovary syndrome (PCOS)." (PMID 41480370, 2025). "In this study, we demonstrated that serum chromogranin A (CgA) levels were significantly elevated in women with polycystic ovary syndrome (PCOS) and showed a positive correlation with body mass index (BMI), insulin, glucose, HOMA-IR, and high-sensitivity C-reactive protein (hs-CRP)." (PMID 41480370, 2025).
pregnancy hypertension (1 paper, 2021). "Until now, only a few studies investigated the role of CgA in pregnancy, however none of these studies focused on PE or pregnancy hypertension." (PMID 34620125, 2021).
prostate small cell carcinoma (1 paper, 2021). A neuroendocrine carcinoma of the prostate gland with unfavorable prognosis, composed of small cells containing neurosecretory granules. "For prostate small cell carcinoma, INSM1 has been shown to be more sensitive (92.3%, 12/13) compared to SYP (84.6%, 11/13) and CgA (53.8%, 7/13), making it the superior NE marker for prostate small cell carcinoma." (PMID 34943408, 2021).
prostate tumors (1 paper, 2025). "For neuroendocrine-differentiated prostate tumors, we demonstrate that xCT is exclusively detected in CgA-positive cells." (PMID 39869598, 2025).
psoriasis (1 paper, 2023). An autoimmune condition characterized by red, well-delineated plaques with silvery scales that are usually on the extensor surfaces and scalp. "Conclusions: sIgA, sAA, and CgA are potential markers of the severity of psoriasis and the associated stress reaction." (PMID 37109650, 2023). "Based on the presented observations, only sIgA and CgA seem to be valuable biomarkers for monitoring the effectiveness of the treatment of psoriasis." (PMID 37109650, 2023). "Based on the presented observations, only sIgA and CgA seem to be valuable biomarkers for monitoring the effectiveness of the systemic treatment of psoriasis." (PMID 37109650, 2023).
pyometra (1 paper, 2015). "The aim of the study was to investigate CgA, measured by Chromogranin A361-372 (Catestatin; Cst) and Chromogranin A17-38 (Vasostatin; VS) in healthy dogs and in dogs with pyometra." (PMID 25636335, 2015). "The aims of the present study were to investigate concentrations of CgA, measured by Cst and VS, in healthy dogs and in dogs with pyometra, and before and after surgery to evaluate a possible diagnostic or prognostic value." (PMID 25636335, 2015). "CgA concentrations were decreased in pyometra, as measured by Cst." (PMID 25636335, 2015). "The reason for the lack of association between CgA and CRP or postoperative hospitalization (as a measurement indicator of morbidity) is unknown, and an association between CgA and mortality remains to be investigated because no dogs died of the pyometra in current study." (PMID 25636335, 2015). "Another explanation for the lower concentrations found in dogs with pyometra could be that negative feedback control of Cst leads to inhibited secretion of catecholamines and CgA, and subsequently decreased CgA concentrations." (PMID 25636335, 2015).
rectal carcinoids (1 paper, 2013). "Among known neuroendocrine markers, SYN, NSE and CgA are relatively specific, and SYN is relatively sensitive in rectal carcinoids." (PMID 23761832, 2013).
Respiratory insufficiency (1 paper, 2022). "Levels of CgA were independent predictors of in-hospital mortality (hazard ratio 1.28 [95% confidence interval 1.077–1.522], p = 0.005) when adjusted for age, number of comorbidities, respiratory insufficiency degree, C-reactive protein levels and time from symptom onset to sampling." (PMID 35468164, 2022).
schizophrenia (1 paper, 2017). A major psychotic disorder characterized by abnormalities in the perception or expression of reality. "Analysis stratified by diagnosis showed that an increase in number of major alleles of rs9658644 was significantly associated with an increase in expression of the CgA protein in the schizophrenia patient group." (PMID 28974776, 2017). "Some of these proteins such as Factor VII, vWF, CgA, AAT and IL-6r have also been found to be altered or predict development of schizophrenia in ultra-high risk or pre-onset individuals." (PMID 28974776, 2017). "However, to our knowledge only SNPs associated with IL-6r, CgA, vWF and AAT have previously been reported in schizophrenia." (PMID 28974776, 2017).
testicular tumors (1 paper, 2019). "In testicular tumors, combining hCG with other similar markers, such as alpha-fetoprotein (AFP), could improve the efficacy of the measurement; however, assessment of hCG and AFP is generally not recommended in NETs, since both lack the sensitivity of specificity of CgA." (PMID 31382663, 2019).
Thrombocytosis (1 paper, 2020). Increased numbers of platelets in the peripheral blood. "Conventional thrombocytosis (platelet count > 400 × 109/L) was observed in two and four cases within the CgA− and CgA+ groups, respectively (p = 0.1642)." (PMID 33383764, 2020). "The different thrombopoietin, CgA, and CgB levels in the CgA+ group suggested a difference in the mechanism of thrombocytosis and chromogranin production, compared to that of CgA− CRC patients." (PMID 33383764, 2020). "Furthermore, both “traditional”- and PIT-based thrombocytosis was more common in the CgA+ group, despite the fact that these patients received aggregation inhibition therapy more frequently." (PMID 33383764, 2020). "Therefore, a prospective cohort pilot study was carried out to search for relationships between CRC and the combined effect of thrombocytosis and CgA+ differentiation." (PMID 33383764, 2020).
thyroid (1 paper, 2021). "It is easy to diagnose and differentiate from other spindle cell lesions of thyroid by histological morphology, immunohistochemical staining with CT, CgA, Syn, CD56, and TTF-1." (PMID 34838061, 2021).
thyroid nodule (1 paper, 2023). A small circumscribed mass in the THYROID GLAND that can be of neoplastic growth or non-neoplastic abnormality. "The tumor cells were confirmed positive for CgA for differential diagnosis from thyroid nodules." (PMID 37867522, 2023).
ureteral tumors (1 paper, 2023). "Since the clinical manifestations and imaging results of ureteral SCNEC are not specific to other types of ureteral tumors, pathological detection of neuroendocrine markers, including the recommended Syn and CgA and CD56, remains an important method for diagnosing ureteral SCNEC." (PMID 37035192, 2023).
urothelial carcinoma (1 paper, 2025). A malignant neoplasm derived from the transitional epithelium of the urinary tract (urinary bladder, ureter, urethra, or renal pelvis). "We first wondered how frequently CGB7 is coexpressed with CGB3, CGB5, CGB8, and CGA in urothelial carcinoma." (PMID 40501795, 2025).
vascular dementia (1 paper, 2020). A degenerative vascular disorder affecting the brain. "In HC subjects, the concentration of CgA was low (3, 77 ± 1.90 pmol/mL), while patients with vascular dementia showed salivary CgA levels (4.04 ± 2.04 pmol/mL) similar to those of the HC subjects." (PMID 32326227, 2020).
vasculitis (1 paper, 2016). "However, our findings raise the possibility that therapies commonly used in patients with vasculitis may indirectly influence vascular events by modulating the CgA system." (PMID 27531191, 2016).
Vertigo (1 paper, 2015). An abnormal sensation of spinning while the body is actually stationary. "CgA levels in patients positively correlated with the frequency of vertigo spells in the previous four weeks (p = 0.008) and negatively with the time in days from the last vertigo attack (p = 0.018)." (PMID 25983374, 2015). "As a consequence, a marked reduction of VS-1/CgA ratio occurs in MD patients with higher recurrence of vertigo spells." (PMID 25983374, 2015). "We found that the relative levels of VS-1 and CgA change in MD depending on the frequency of vertigo spells and the time from the last attack." (PMID 25983374, 2015). "Serum levels of CgA positively correlated with the vertigo frequency occurring within 30 days before blood collection (rs stat 0.43; p = 0.008) and negatively correlated with the time in days from the last vertigo attack (rs stat −0.39; p = 0.018)." (PMID 25983374, 2015). "Notably, subjects with values greater than the median CgA value (0.75 nM) had a higher number of vertigo spells in the last month (4 ± 2.4 versus 2.3 ± 0.8, p = 0.011)." (PMID 25983374, 2015). "Furthermore the VS-1/CgA ratio positively correlates with the time from the last attack, pointing to a possible change in the proteolytic processing of CgA or to differential secretion or metabolism of these polypeptides in patients with increased clustering of vertigo." (PMID 25983374, 2015). "The results show that variations of CgA levels, but not of VS-1, occur in the blood of patients with active MD, depending on the frequency of vertigo spells and the time from the last crisis." (PMID 25983374, 2015). "The results indicate that variations of CgA levels, but not of VS-1, occur in the blood of patients with active MD, depending on the frequency of vertigo spells and the time from the last crisis." (PMID 25983374, 2015). "Consequently we observed a negative correlation between the VS-1/CgA ratio and vertigo frequency in the last 30 days (Spearman; rs = −0.36; p = 0.029) and a positive correlation with the time in days from the last crisis (rs = 0.47; p = 0.003)." (PMID 25983374, 2015).